HLA-DQB1 (major histocompatibility complex, class II, DQ beta 1)
Description:
Binds peptides derived from antigens that access the endocytic route of antigen presenting cells (APC) and presents them on the cell surface for recognition by the CD4 T-cells. The peptide binding cleft accommodates peptides of 10-30 residues. The peptides presented by MHC class II molecules are generated mostly by degradation of proteins that access the endocytic route, where they are processed by lysosomal proteases and other hydrolases. Exogenous antigens that have been endocytosed by the APC are thus readily available for presentation via MHC II molecules, and for this reason this antigen presentation pathway is usually referred to as exogenous. As membrane proteins on their way to degradation in lysosomes as part of their normal turn-over are also contained in the endosomal/lysosomal compartments, exogenous antigens must compete with those derived from endogenous components. Autophagy is also a source of endogenous peptides, autophagosomes constitutively fuse with MHC class II loading compartments. In addition to APCs, other cells of the gastrointestinal tract, such as epithelial cells, express MHC class II molecules and CD74 and act as APCs, which is an unusual trait of the GI tract. To produce a MHC class II molecule that presents an antigen, three MHC class II molecules (heterodimers of an alpha and a beta chain) associate with a CD74 trimer in the ER to form a heterononamer. Soon after the entry of this complex into the endosomal/lysosomal system where antigen processing occurs, CD74 undergoes a sequential degradation by various proteases, including CTSS and CTSL, leaving a small fragment termed CLIP (class-II-associated invariant chain peptide). The removal of CLIP is facilitated by HLA-DM via direct binding to the alpha-beta-CLIP complex so that CLIP is released. HLA-DM stabilizes MHC class II molecules until primary high affinity antigenic peptides are bound. The MHC II molecule bound to a peptide is then transported to the cell membrane surface. In B-cells, the interaction between HLA-DM and MHC class II molecules is regulated by HLA-DO. Primary dendritic cells (DCs) also to express HLA-DO. Lysosomal microenvironment has been implicated in the regulation of antigen loading into MHC II molecules, increased acidification produces increased proteolysis and efficient peptide loading.
Synonyms: HLA-DQB; IDDM1; CELIAC1
Safety:
Unwanted effects reported when the protein is acted on. In parentheses: how it was acted on, where the effect was seen, and who reports it.
agranulocytosis (source: ClinPGx)
drug hypersensitivity reactions (source: ClinPGx)
drug induced liver injury (source: ClinPGx)
liver injury (source: ClinPGx)
narcolepsy (source: ClinPGx)
Pegaspargase Hypersensitivity (source: ClinPGx)
severe cutaneous adverse reactions (source: ClinPGx)
Gene: Protein-coding gene on chromosome 6 (32,659,467 to 32,668,383, reverse strand). Ensembl gene ENSG00000179344.
Subcellular location: Cell membrane; Endoplasmic reticulum membrane; Golgi apparatus, trans-Golgi network membrane; Endosome membrane; Lysosome membrane
Subcellular location (Human Protein Atlas): Rods & Rings; Golgi apparatus
Pathways (Reactome):
Immune System: Interferon gamma signaling
Genetic constraint (gnomAD): Loss-of-function variants: 5 observed, 4.76 expected, observed/expected ratio (o/e) 1.05, 90% interval 0.54 to 1.83. That is too few expected variants to judge how well the gene tolerates losing a copy. Missense variants: 80 observed, 86.19 expected, observed/expected ratio (o/e) 0.93, 90% interval 0.77 to 1.12. Synonymous variants: 32 observed, 29.13 expected, observed/expected ratio (o/e) 1.1, 90% interval 0.83 to 1.48.
Homologues: Orthologues: chimpanzee HLA-DQB1 (91% identical), pig SLA-DQB1 (74% identical). Paralogues in human: HLA-DQB2 (79% identical), HLA-DRB5 (66% identical), HLA-DRB1 (64% identical), HLA-DPB1 (61% identical), HLA-DOB (55% identical), HLA-DOA (22% identical), HLA-DPA1 (22% identical), HLA-DQA1 (22% identical), HLA-DRA (21% identical), HLA-DQA2 (20% identical), HLA-DMB (19% identical), HLA-DMA (16% identical), and 1 more.
Diseases named in the same sentence as HLA-DQB1 in open-access papers:
HLA-DQB1 is named in the same sentence as 203 diseases in open-access papers, as found by Europe PMC text mining. Sharing a sentence is not in itself a finding about the gene and the disease. The quoted sentences say what the papers report.
type 1 diabetes (43 papers, 2002 to 2026). "In this study, the effect of HLA-DQB1*03:02 and the tagging SNP rs9273363 on type 1 diabetes risk varied by ancestry." (PMID 41037100, 2026). "In the case of pocket 9, the β57Asp/Ala dimorphism seen, respectively, in the vast majority of type 1 diabetes resistant vs susceptible HLA-DQB1 molecules is responsible for the anchor choice of small aliphatic vs acidic residues." (PMID 39354095, 2024). "HLA-DRB1*0801 and HLA-DQA1*0401 are in strong LD with HLA-DQB1*0402 (P = 5.2 × 10−8) and have been associated with autoimmune disease, including type 1 diabetes and systemic lupus erythematosus." (PMID 36929174, 2023). "Risk can be independently conferred by DQ and DR alleles: for instance, type 1 diabetes risk is independently associated with both DQ2.5/8 alleles (HLA-DQB1*0201/HLA-DQB1*0302) and DR3/4 alleles (HLA-DRB1*0301/ HLA-DRB1*0405, HLA-DRB1*0401)." (PMID 33262997, 2020). "HLA-DQB1 is one of the high-risk candidate genes for several diseases, such as type 1 diabetes and breast cancer." (PMID 32375827, 2020). "A number of studies have identified the association of HLA-DQB1 with thyroiditis (notably autoimmune Hashimoto’s thyroiditis) and type 1 diabetes." (PMID 30978214, 2019). "Three of the 11 independent amino acid variations, HLA-DRB1 residue 67 and 71, HLA-DQB1 residue 55 are associated with type 1 diabetes, multiple sclerosis, hypothyroidism, rheumatoid arthritis, and inflammatory polyarthritis according to PheWAS database." (PMID 31543879, 2019). "Umbilical cord serum samples from 764 children born from 1994 to 2004 with HLA-DQB1 conferred risk for T1D participating in the Type 1 Diabetes Prediction and Prevention Study were analyzed for 25(OH)D using an enzyme immunoassay." (PMID 30657906, 2019). "Regions on or close to HLA-DQB1 (6p21.3) were frequently identified by GWAS as susceptibility loci for many complex diseases, such as lymphoma, type 1 diabetes, asthma, systemic sclerosis, and narcolepsy." (PMID 25784652, 2015). "HLA-DQB1 is among the most relevant HLAs for genetic predisposition since it was identified to be highly probable to contain methylation-variable positions, possibly indicating an early etiological state in the development of type I diabetes." (PMID 33401659, 2021). "We then took a candidate SNP approach and extracted all type 1 and type 2 diabetes-associated SNPs; the strongest type 1 diabetes-associated signal was in the HLA-DQB1 region (rs1063355, p = 6.28 × 10−6); however, no type 2 diabetes-associated loci achieved significance." (PMID 32705316, 2020). "In addition, HLA-DQB1 was closely associated with multiple autoimmune-related diseases, such as multiple sclerosis and type I diabetes." (PMID 28743287, 2017). "We can only speculate on why PA is associated with a lower incidence of LADA only in individuals without genetic susceptibility to diabetes; the HLA-DRB1 and HLA-DQB1 genotypes are the main risk factors for β-cell autoimmunity and loss of β-cell function leading to type 1 diabetes." (PMID 32835373, 2020). "Although HLA-DRB1*15:03 is on the same haplotype, with HLA-DQB1*06:02, this African-specific haplotype could well have different sequences affecting class II gene expression or structure, that increase its predisposition to Type 1 diabetes." (PMID 23398374, 2013). "Twin and family studies demonstrate that genetic factors contribute to ~50% of the risk of type 1 diabetes, with variation in HLA class I (HLA-A, HLA-B, HLA-C) and HLA class II (HLA-DRB1, HLA-DQA1, HLA-DQB1) accounting for 30%- 50% of genetic risk." (PMID 40832419, 2025). "Highly associated pathways such as KEGG "Type I Diabetes," "Antigen processing and presentation," and "Systemic lupus erythematosus" share several genes, particularly HLA class I and II paralogs (HLA-DRB1, HLA-DQB1, HLA-DQA1, HLA-B)." (PMID 39495786, 2024).
type 1 diabetes (continued). "An increase in H3K9ac levels at the same promoter regions of HLA-DQB1, which was hyperacetylated in type I diabetes patients was found after Interferon gamma (IFNγ) and TNFα stimulation." (PMID 33401659, 2021). "The index SNP in the MHC was rs9273363 (p = 2.16 × 10−35), which has previously been shown to be associated with type 1 diabetes, to tag the HLA DQB1*03:02 genotype and to be located in a potential enhancer region of the major type 1 diabetes gene, HLA-DQB1." (PMID 28983737, 2018). "It is beyond the scope of the current study to consider fine-mapping of the MHC region, and it is well established that the HLA-DQB1, HLA-DRB1, HLA-A and HLA-B genes are the primary determinants of the MHC risk in type 1 diabetes." (PMID 28983737, 2018). "HLA-DQA1 alleles were also very strongly associated with Type 1 diabetes in African Americans, reflecting the strong linkage disequilibrium with highly disease-associated HLA-DRB1 and HLA-DQB1 alleles." (PMID 23398374, 2013). "Using the WTCCC type 1 diabetes data, we were able to accurately assess the risk of haplotypes spanning HLA-DRB1, HLA-DQA1 and HLA-DQB1." (PMID 23762245, 2013). "The MHC region at chromosomal position 6p21 encodes many genes (such as HLA-DQB1 and HLA-DRB1) that have been associated with type 1 diabetes by using the single-locus test." (PMID 21569557, 2011). "Twin and family studies have demonstrated that genetic factors contribute to approximately 50% of the risk for type 1 diabetes, with variations in HLA class I (HLA-A, HLA-B, HLA-C) and HLA class II (HLA-DRB1, HLA-DQA1, HLA-DQB1) accounting for 30–50% of the genetic risk." (PMID 41037100, 2026). "As expected, HLA-DQB1*03:02 was most strongly associated with T1D risk in the EUR and FIN groups, while in the AFR and AMR groups, the most strongly associated HLA class II allele was HLA DQA1*03:01, which aligns with our previous findings from recent type 1 diabetes GWAS." (PMID 40832419, 2025). "Additionally, previous studies have shown that HLA-DQB1 genotypes are most frequent in early-onset classic type 1 diabetes patients who were diagnosed at <20 years, followed by late-onset classic type 1 diabetes patients who were diagnosed at >35 years and LADA patients." (PMID 35992113, 2022). "In these studies, HLA-DQB1 was considered to be a genetic susceptibility locus not only for type 1 diabetes mellitus but also for allergic sensitization which might have been the reason for higher correlation of all the tested variables." (PMID 32784846, 2020). "In cluster 2, the significantly enriched genes were HLA-B, HLA-A, HLA-DRB1, HLA-DQA1 and HLA-DQB1, with all genes related to allograft rejection, GVHD, type I diabetes, autoimmune thyroid disease and viral myocarditis." (PMID 37063831, 2023). "We also identified several COPD-associated genes enriched for immune processes and immune-related diseases (e.g., HLA-C and HLA-DQB1—antigen processing and presentation, HLA-DQB1—type I diabetes mellitus, influenza A, autoimmune thyroid disease)." (PMID 36574990, 2023). "In contrast, the effect size for HLA-DQB1*03:02 allele tagged by this SNP differs among the AFR (OR=1.68; the HLA-DQA1*03:01 allele is most strongly associated with type 1 diabetes risk, with effect OR=5.45), AMR (not significant in this group), EUR (OR=5.33) and FIN (OR=3.91) groups." (PMID 41037100, 2026). "Three SNP-diagnosis pairs passed the PheWAS significance threshold: rs9273349 (HLA-DQB1) and E06 (thyroditis); rs9273349 (HLA-DQB1) and E10 (type-1 diabetes); and rs2281135 (PNPLA3) and K76 (non-alcoholic liver diseases, including NAFLD)." (PMID 30978214, 2019). "Research design and methods: Three loci(HLA-DQB1, DQA1 and CTLA-4) were analysed in 62 type 1 diabetic patients, 72 firstdegreerelatives and 84 nondiabetic controlsubjects by means of PCR-RFLP." (PMID 11900275, 2002).
asthma (28 papers, 2010 to 2025). "Genetic polymorphisms of HLA-DQA1 and HLA-DQB1 have also been linked to asthma susceptibility in the northern Chinese population." (PMID 39766875, 2024). "For the HLA analysis, HLA-B*40:02 and HLA-DRB1*04:05, HLA-B*40:02, HLA-C*04:01, and HLA-DRB1*04:05, and HLA-DRB1*03:01 and HLA-DQB1 were significantly associated with late-onset asthma in all, White, and Black participants." (PMID 37415598, 2023). "For example, HLA-DQB1*02:01:01 was associated with a 1.09-fold increase in odds of asthma (95% CI: 1.06–1.12, p = 1.25 × 10−10), HLA-DQB1*02:01:08 was associated with a 0.90-fold decrease in risk (95% CI: 0.87–0.93, p = 5.90 × 10−11)." (PMID 37923823, 2023). "In European‐descent populations, CDHR3, CTNNA3, and HLA‐DQB1 have been associated with severe asthma exacerbations." (PMID 35754128, 2022). "In contrast, the minor T allele of two SNPs in HLA-DQB1 (rs9273349 and rs1063355) seems to confer protection to both asthma and T1DM." (PMID 34071190, 2021). "In a two-stage cases-control study, we revealed a variant within HLA-DQB1 significantly associated with asthma risk (rs1049213, meta-analysis p = 1.30 × 10–7, OR [95% CI] = 1.74 [1.41–2.13]) previously associated with asthma and broad allergic phenotype." (PMID 34880287, 2021). "In fact, a number of genetic variants from the MHC (some of them linked to HLA-DQA1 and HLA-DQB1) have been associated with asthma in large genetic association studies." (PMID 34880287, 2021). "HLA-DQB1 and HLA-DRA have both been previously been associated with asthma, but each has also been associated to another phenotype; HLA-DQB1 to hypothyroidism and HLA-DQB1 to RA." (PMID 32245788, 2020). "HLA-DQB1*03 and HLA-DRB1*13 have also been associated with A. alternata moderate to severe asthma in children, where HLA-DQB1*03 was reduced in frequency and HLA-DRB1*13 increased in frequency when compared to A. alternata mild asthmatic children." (PMID 31824491, 2019). "We identified eight eGenes whose eQTL colocalized with GWAS signals for pulmonary diseases, of which three, HLA-B, HLA-DQA1 and HLA-DQB1, had been previously associated with Asthma in GWAS and in the UK Biobank." (PMID 31746734, 2019). "As for genetics, HLA-DRB1 and HLA-DQB1 genes were independently associated with asthma and its related traits in numerous candidate gene association studies, and HLA-DRB1 was found to be the major determinant of the association with RA susceptibility." (PMID 29849649, 2018). "The minor allele at these two SNPs (T) in HLA-DQB1 confers protection in both asthma (odds ratio = 0.85) and T1D (odds ratio = 0.28; 20)." (PMID 22069270, 2011). "While previous asthma GWAS have implicated the classical and highly polymorphic HLA-DQA1 and HLA-DQB1 class II genes, our study revealed associations with HLA-DQA2 and HLA-DQB2 genes in risk for AOA." (PMID 35606880, 2022). "These were in loci previously associated with asthma exacerbations (GSDMB, RAD50, HLA‐DQB1, ADAM33, VDR, and CDHR3) or moderate‐to‐severe asthma (IKZF3, TSLP, MUC5AC, C11orf30, SMAD3, and WDR36)." (PMID 35754128, 2022). "Fine-mapping the HLA region suggested that there are at least two asthma association signals in this region and that amino acid changes in HLA-DQA1, HLA-DQB1 and HLA-DRB1 genes are most likely to be the underlying causal variations." (PMID 35597955, 2022). "At least two independent loci characterised by amino acid changes in the HLA-DQA1, HLA-DQB1 and HLA-DRB1 genes are likely to account for association of SNPs and CNVs in this region with asthma." (PMID 35597955, 2022). "This evidence agrees with human transcriptomic observations revealing a reduction of the HLA-DQA1 and HLA-DQB1 lung gene expression in patients with severe asthma compared to healthy controls." (PMID 34880287, 2021). "For example, 4 genes of C2CD2, HLA-DRB6, LPCAT2, and HLA-DQB1 were associated with TB risk, and RUNX showed association with asthma or allergic disease risk." (PMID 33051402, 2020).
asthma (continued). "This study evaluated 8 of these genes (IL4, IL13, TNF-α, HLA-DRB1, HLA-DQB1, FCER1B/MS4A2, CD14, ADAM33) as well as 3 glutathione-s-transferase genes (GSTM1, GSTP1, and GSTT1) for association with asthma/allergy among urban-residing African Americans." (PMID 21320344, 2011). "Among the asthma genes identified in genome wide association studies, ROBO1, RORA, HLA-DQB1, IL2RB and PDE10A were differentially expressed during human lung development." (PMID 21699702, 2011). "These preliminary results of decreased frequency of HLA-DQB1*03 in Alternaria-sensitive moderate-severe asthma in children is similar to that found in ABPA where HLA-DQB1*02 was decreased." (PMID 20298583, 2010). "Interestingly, certain HLA gene variants such as HLA-DQA1, HLA-DQB1, and HLA-DRB9 are also associated with asthma." (PMID 40661126, 2025). "Two signals are known to be associated with asthma and COPD/lung function, including the HLA-DQB1 locus (the first signal identified as associated with both asthma and COPD), and a signal at C5orf56, encoding IRF1-AS1, on chromosome 5, near a cytokine gene cluster." (PMID 35104449, 2022). "A recent study reported colocalizations between eQTLs for HLA-B, HLA-DQB1, HLA-DQA1, HLA-DRA, TAP1, and RNF5 in induced pluripotent stem cells with asthma GWAS SNPs." (PMID 35606880, 2022). "Two ACO signals have previously been reported separately for both asthma and lung function or COPD: rs9273410 in HLA-DQB1 (EAF, 0.445; OR, 1.20; P = 9.19 × 10–28) and rs3749833 in C5orf56 (EAF, 0.263; OR, 1.12; P = 9.37 × 10–12)." (PMID 35104449, 2022). "These signals suggest a spectrum of shared genetic influences, some predominantly influencing asthma (FAM105A, GLB1, PHB, TSLP), others predominantly influencing fixed airflow obstruction (IL17RD, C5orf56, HLA-DQB1)." (PMID 35104449, 2022). "Among the asthma genes identified in GWAS, ROBO1, RORA, HLA-DQB1, IL2RB and PDE10A showed most significant evidence of involvement in lung development (all adjusted p < 0.001 for differential expression)." (PMID 21699702, 2011). "Among the GWAS asthma genes, ROBO1, RORA, HLA-DQB1, IL2RB and PDE10A were differentially expressed in the human data." (PMID 21699702, 2011). "Among genes identified in asthma GWAS, ROBO1, RORA, HLA-DQB1, IL2RB and PDE10A showed most consistent expression patterns and from asthma candidate genes, e.g. NOD1, EDN1, CCL5 and HLA-G were identified." (PMID 21699702, 2011). "Finally, transcriptomic data from bronchial brushing and bronchoalveolar lavage (BAL) samples revealed that HLA-DQA1 (only available for bronchial brushing), HLA-DQB1, and HLA-DRB1 were downregulated in patients with severe asthma compared to healthy controls." (PMID 34880287, 2021).